CD274 (CD274 molecule)
Diseases named in the same sentence as CD274 in open-access papers (continued):
Sharing a sentence is not in itself a finding about the gene and the disease.
Autoimmunity (272 papers, 2010 to 2026). The occurrence of an immune reaction against the organism's own cells or tissues. "The CD274 gene encodes the immune inhibitory ligand PD-L1, which binds to the PD-1 receptor, blocking T-cell activation to prevent autoimmunity, a mechanism also used by the tumor to escape immune surveillance." (PMID 40362483, 2025). "CD274 encodes a receptor ligand that binds to PD-1 receptors on T-cell surfaces, inhibiting T-cell activation and antibody production – an essential process for preventing autoimmunity." (PMID 35716830, 2022). "The protein encoded by CD274 is a ligand, also known as the Programmed death-ligand 1 (PD-L1), which interacts with its receptor the programmed cell death-1 (PD-1) to inhibit cytokine production and prevent autoimmunity, thereby maintaining immune homeostasis." (PMID 41272439, 2025). "PD-1 is a T-cell immune checkpoint that suppresses autoimmunity and promotes immune tolerance in cells expressing PD-L1 (B7-H1; CD274) and PD-L2 (B7-DC)." (PMID 39940924, 2025). "PD-1 (CD279) is a T-cell immune checkpoint that suppresses autoimmunity, leading to immune tolerance of cells expressing programmed death-ligand 1 (PD-L1, CD274)." (PMID 34064074, 2021). "It is commonly accepted that PD-L1 (i.e. CD274, B7-H1) precludes autoimmunity by engaging to the PD-1 receptor (i.e. CD279) on activated T cells." (PMID 30633154, 2019). "PD-L1 (also known as B7-H1 or CD274) is one of the ligands of PD-1, an immune checkpoint which prevents T cell activation and limit autoimmunity leading to self-tolerance." (PMID 28804523, 2017). "PDCD1 is a ligand of CD274 and is involved in safeguarding against autoimmunity." (PMID 36158806, 2022). "CD274 programmed death protein ligand 1 (PD-L1, CD274, B7-H1) has been shown to play a role in the regulation of immune responses and peripheral tolerance, and play a critical role in the induction and maintenance of tolerance to autoimmunity." (PMID 36226166, 2022). "Programmed cell death protein (PD-1) and its ligand PD-L1 (CD274) form a key immune checkpoint pathway that downregulates T-cell activation to maintain peripheral tolerance and prevent autoimmunity." (PMID 41465349, 2025). "Recent years, PDCD1 (PD-1), CD274 (PD-L1) and CTLA4 have been confirmed to act as immune checkpoints and can prevent the immune system from killing cancer cells by inhibiting autoimmunity." (PMID 36845098, 2023). "Immune checkpoints such as PD-L1 (CD274) serve to dampen the reactivity of the immune system and to prevent autoimmunity." (PMID 31681559, 2019). "Programmed Death 1 (PD-1, CD279) and its ligand Programmed Death Ligand 1 (PD-L1, CD274) are transmembrane proteins with role in autoimmunity, infection and anti-tumor immune response." (PMID 31581535, 2019). "CD274 (also known as B7-H1) and its paralog, PDCD1LG2 (programmed cell death 1 ligand 2, also known as B7-DC), are types of transmembrane protein normally expressed on immunocytes, which function in preventing autoimmunity under infected conditions." (PMID 28286742, 2017). "Herein, we initially identified a set of 12 surface molecules, including CD39, CD229, CD81, CD326, CD54, CD130, CD49d, CD172a, CD274, CD155, CD205, and CD47 that are highly expressed by ASCs, and specifically identify ASCs in naive WT mice as well as in the contexts of immunization and autoimmunity." (PMID 35464469, 2022).
esophageal cancer (262 papers, 2012 to 2026). A primary or metastatic malignant neoplasm involving the esophagus. "Induction of EMT in breast and esophageal cancer cells is associated with immune evasion, notably through the expression of another immune checkpoint factor, PD-L1 (or CD274)." (PMID 38506114, 2024). "Typically, the abnormal expression level of CD274 and PDCD1LG2 was detected in both esophageal carcinoma (ESCA) and stomach adenocarcinoma (STAD), where PDCD1LG2 was related to the overall survival (OS) of the patients in ESCA (p = 0.015) and STAD (p = 0.025)." (PMID 33833994, 2021).
Sepsis (258 papers, 2010 to 2026). Sepsis is defined as life-threatening organ dysfunction caused by a dysregulated host response to infection. "The observed association of ACOD1 and CD274 with inflammatory markers in patients further reinforces the potential role of this axis in sepsis pathogenesis." (PMID 40703506, 2025). "As a result, the ratio of variant 1 to CD274-L2A was elevated in monocytes and neutrophils from sepsis patients (32 and 34, respectively), in comparison with B cells from the same patients, where it was inverted (0.6) (p≤0.004, one-way ANOVA)." (PMID 31729316, 2019). "Therefore, development of strategies targeting CD274 signals provides a novel and promising approach to manipulate the devastating diseases associated with sepsis." (PMID 23585913, 2013). "The immunosuppressive phase of sepsis is characterized by altered expression levels of immunosuppressive‐related genes such as CD274 (PD‐L1) and HLA‐DR." (PMID 39887584, 2025). "CD64 expression was raised in severe/critical COVID-19 and further elevated in sepsis, together with increased PD-L1 (CD274) expression." (PMID 35216673, 2022). "EZH2 was positively correlated with CD274 (PD-L1) in both sepsis and NSCLC, and the correlation was statistically significant." (PMID 36552722, 2022). "In sepsis, high monocytic PD-L1/CD274 expression has been correlated with increased T-cell apoptosis, lymphopenia, and T-cell dysfunction." (PMID 33066260, 2020). "A subsequent study reported that sepsis enhanced expression of PD-1 on peripheral T cells and programmed cell death 1 ligand (PD-L1 or CD274) on spleen B cells and monocytes in a cecal ligation and puncture (CLP) model." (PMID 32719675, 2020). "In contrast, expression of CD274-L2A was disproportionately reduced in monocytes and neutrophils isolated from sepsis patients, in comparison with the same cell types from healthy individuals, whereas expression of variant 1 remained elevated." (PMID 31729316, 2019). "The expression of SLC31A1, CD274, ATOX1, MTF1, UBE2D1, DLD, and VEGFA was found to be upregulated, while that of DLST, UBE2D2, COX11, DLAT, GLS, FDX1, and ULK2 were significantly downregulated in patients with sepsis-associated ALI." (PMID 38779731, 2025). "Together with the results from CLP sepsis mice, we considered CD274+IL1RN+ mature neutrophils to be immunosuppressive effector cells in the lung environment during sepsis‐induced immunosuppression, which can transition from intermediate‐state CXCR2+ neutrophils." (PMID 39887584, 2025). "Recently, the programmed cell death receptor-1 (PD-1)—also called CD279—and one of its two primary ligands, programmed cell death ligand-1 (PD-L1)—also called B7-H1 or CD274—have gained importance with respect to the pathophysiology of sepsis and as a novel drug target for therapy." (PMID 35732880, 2022). "Notably, LPS increased neutrophil expression of CD274 (PD-L1), which is consistent with other stimulants of sepsis, such as IL-1β, HMGβ1, G-CSF and IL-4." (PMID 33549126, 2021). "Sepsis is associated with elevated serum levels of IFNs and MS patients are treated with recombinant IFN-β, allowing analysis of the in vivo effect of IFNs on PD-L1 variant 1 and CD274-L2A expression." (PMID 31729316, 2019). "This indicates that higher expression of CD274 might indicate a better outcome in sepsis patients." (PMID 38239341, 2023). "Even when administered after the onset of sepsis, pramipexole significantly improved survival rates, reduced pro-inflammatory cytokine levels, attenuated organ damage, and downregulated ACOD1 and CD274 expression." (PMID 40703506, 2025). "PD‐1 (CD279) and its two ligands, PD‐L1 (CD274) and PD‐L2 (CD273) constitute a complex system of negative regulators involved in controlling T‐cell responses in sepsis." (PMID 38270311, 2024). "Immune checkpoint-related genes CD274 (PD-L1), HAVCR2 (TIM3), and SIGLEC15 were overexpressed in sepsis." (PMID 35844488, 2022).
Sepsis (continued). "We observed the identical trend regarding the protein expression of mregDC marker genes, including CCR7, CD274 (PD-L1), and CD80, which were consistently upregulated and enriched at 24 h after sepsis." (PMID 35832091, 2022). "Our analysis showed that multiple immune checkpoints (CD274 [coding PD-L1], HAVCR2 [coding TIM3], and SIGLEC15 [coding SIGLEC-15]) were also highly expressed in sepsis." (PMID 35844488, 2022). "EZH2 was positively correlated with CD274 (PD-L1) and PDCD1 (PD-1) expression in sepsis, with statistical significance." (PMID 36552722, 2022). "In our study, the level of EZH2 was positively related to macrophages, NK cells, neutrophils, Th1, Th2, Th17, and CD274 (PD-L1) in both NSCLC and sepsis datasets." (PMID 36552722, 2022). "Additionally, CD274 and CASP3 reflect pathways of immune exhaustion and apoptosis, respectively, both of which are significant markers of sepsis progression." (PMID 41252417, 2025). "Consistent with the observation of the increase in CXCR2+ and CD274+IL1RN+ neutrophil subpopulations in sepsis, the amplification of CXCR2+ and PD‐L1+ subpopulations was observed in both blood and BALF neutrophils in immunosuppressive sepsis patients." (PMID 39887584, 2025). "Meanwhile, CD274, PDCD1LG2, and SLGLEC15 were upregulated in sepsis, but these changes were not statistically significant." (PMID 40070882, 2025). "Besides, the relative composition of CXCR2+ N00 and CD274+IL1RN+ N02 was also increased in immunosuppressive sepsis BALF, indicating that the N00 and N02 neutrophil subpopulations might be more crucial to sepsis‐induced immunosuppression than other subpopulations." (PMID 39887584, 2025). "Notably, N02 characterized by IL1RN and CD274 was unique to BALF and absent in peripheral blood, suggesting a distinct population in the lung environment of sepsis patients." (PMID 39887584, 2025).
osteosarcoma (244 papers, 2014 to 2026). A usually aggressive malignant bone-forming mesenchymal neoplasm, predominantly affecting adolescents and young adults. "Immune checkpoint analysis of CD270 (HVEM), CD274 (PD-L1), and CD276 (B7H3) showed higher expression levels in metastases compared to the parental osteosarcomas, with CD274 as well as CD276 also being associated with poorer patient survival." (PMID 37048099, 2023). "Beside these, we do not see any significant correlation between expression levels of CD274 and PDCD1LG2 genes, that encodes PD-L1 and PD-L2 respectively, with the expression levels of PDCD1 and IFNG, and the percentage of CD8 T cells in osteosarcoma tumors." (PMID 33757216, 2021). "In this study, we noted a higher expression level of the ICGs (CTLA4, CD274, PDCD1C, HAVCR2, and LAG3) in the osteosarcoma patients categorized into the low‐risk group, which suggested that these patients could gain more benefits from the immune checkpoint blockade therapy." (PMID 36129020, 2023). "This study found that macrophage M1 was positively correlated with immune checkpoints PDCD1, CD274 (PD-L1), PDCD1LG2, CTLA4, and TIGIT, suggesting the opportunity of ICBs therapy in osteosarcoma patients with high infiltrating macrophage M1." (PMID 34335756, 2021).
autoimmune disease (240 papers, 2011 to 2026). A disorder resulting from loss of function or tissue destruction of an organ or multiple organs, arising from humoral or cellular immune responses of the individual to their own tissue constituents. "Polymorphisms on CD274 are however known to be associated with multiple autoimmune diseases, such as type 1 diabetes, ankylosing spondylitis, and Graves’ disease as well as autoimmune Addison’s disease." (PMID 35053465, 2022). "In human, the clinical relevance of genetic polymorphisms in the human CD274 gene, encoding PD-L1, has been reported in several autoimmune diseases, such as Addison’s disease and Graves’ disease." (PMID 29728568, 2018). "CD274 (PD-L1), CXCL13, BIRC5, and SMPD3 play the following roles in the IL-17a and IL-23 pathways: CD274 (PD-L1): The IL-17a and IL-23 pathways are closely related to the pathogenesis of autoimmune diseases like psoriasis." (PMID 40557155, 2025). "Programmed cell death ligand 1 (PD-L1), also known as CD274, is known to control adaptive immune responses during various pathological conditions such as autoimmune diseases, infections, and cancer." (PMID 37497456, 2023). "Previous experiments on knockout mice revealed that the PDCD1/CD274 system has most likely evolved as means to ensure immunological tolerance to self-tissue, as mice deficient in PDCD1 suffer from spontaneous autoimmune diseases." (PMID 25940792, 2015). "Aberrant expression and dysregulation of CD274 have been reported during bacterial infection, inflammation and in numerous autoimmune diseases." (PMID 23585913, 2013). "Unexpectedly, CD274 molecule, which has been speculated to play a major role in suppressing the immune system during autoimmune disease and disease states, including hepatitis, is down-regulated by IGKV3-20 in PBMCs of MML while strongly up-regulated in all the other HCV-positive samples." (PMID 24428943, 2014). "CD274 (up-regulated 4.11-fold) also known as programmed cell death 1 ligand 1 (PD-L1), which has been speculated to play a major role in suppressing the immune system during particular events such as pregnancy, tissue allografts, autoimmune disease and other disease states." (PMID 25098731, 2014). "PD-1 and its ligand PD-L1, also known as B7 homolog 1 (PD-L1, B7-H1, CD274), represent one of the most studied immune checkpoints in cancer and autoimmune disease." (PMID 40385641, 2025). "Programmed cell death 1 (PD-1; also known as PDCD1) and programmed death-1-ligand 1 (PD-L1; also known as CD274) play important negative regulatory roles in inflammation, autoimmune diseases, and tumors." (PMID 33521133, 2021). "Additional immune-regulatory loci include MICA/MICB, CTLA4, PTPN22, CIITA, CLEC16A, CD274 (PD-L1), and NLRP1 (NALP1)—variants shared with other autoimmune diseases, underscoring common immune checkpoints rather than AAD-specific genes." (PMID 41465179, 2025). "PD-L1, also known as CD274 or B7-H1, is a fundamental trans-membrane protein involved in the repression of the immune response during pregnancy, allograft, autoimmune diseases and other diseases such as hepatitis." (PMID 33488524, 2020).
Hodgkins lymphoma (233 papers, 2012 to 2025). A heterogeneous group of malignant lymphoid neoplasms of B-cell origin characterized histologically by the presence of Hodgkin and Reed-Sternberg (HRS) cells in the vast majority of cases. "For example, an increased copy number of the genetic locus encoding CD274, the gene responsible for PD-L1 protein synthesis, was found in patients with Hodgkin’s lymphoma and small-cell lung cancer (SCLC)." (PMID 39941003, 2025). "Copy number alterations (CNAs) resulting in amplification of CD274 in Hodgkin's lymphoma are associated with high response rates to PD‐L1 inhibitors." (PMID 33314633, 2021). "The mechanisms underlying increased PD-L1 expression in Hodgkin lymphoma include genetic amplification of CD274 (encoding PD-L1) and constitutive AP1 signaling." (PMID 27012666, 2016). "Large-scale genomic alterations, especially CD274/PD-L1 gene amplification, have great impact on anti-PD-1 efficacy on cancers such as Hodgkin’s lymphoma." (PMID 36894899, 2023). "Recently in classic Hodgkin lymphoma, a 9p24.1 amplification involving CD274 (PD-L1) and PDCD1LG2 (PD-L2) was shown to predict response to nivolumab outcomes." (PMID 34234122, 2021). "In Hodgkin lymphoma alterations in chromosome 9p24.1 leads to PD-L1 (CD274) and PD-L2 (PDCDLG2) gene amplification in RS cells." (PMID 27861596, 2016). "Furthermore, in Hodgkin lymphoma, chromosomal abnormalities of 9p24.1,a genomic region that includes CD274, PDCD1LG2 (encoding PD-L), and Janus kinase 2(JAK2), have been correlated with increased PD-L1 expression." (PMID 26361042, 2015). "Finally, amplification of PD-L1 (CD274) on chromosome 9p by neoplasms is well documented in Hodgkin lymphoma; one might hypothesize that, considering its known immuno-suppressive role, amplification of the PD-L1 genomic region could be an active immuno-evasion mechanism in multiple tumor types." (PMID 28749946, 2017). "PD-L1 status may be genetically upregulated in cancer cells, e.g., via PD-L1 (CD274) gene amplification (a good example is Hodgkin lymphoma)." (PMID 35964287, 2023). "In the group of patients presenting a nodular sclerosis subtype, the immune profile switched at relapse, with an upregulation of LGALS1 and TGFB1 and downregulation of CD163, CD274, HGF, IL15, and ICOS." (PMID 36230815, 2022).
sarcoma (231 papers, 2013 to 2026). A usually aggressive malignant neoplasm of the soft tissue or bone. "Lastly, the CD274 gene, which encodes the PD-L1 protein, was amplified in 1.0% (75/7594) of all sarcomas, with the highest rates of amplification in UPS/MFH (3.6%), myxofibrosarcoma (2.6%) and sarcoma NOS (2.2%)." (PMID 35705558, 2022). "The expression of PD-L1 was assessed in 1064 cell lines on the CCLE website, and the average CD274 (PD-L1) expression was low in 29 sarcoma cell lines compared to tumor cell lines derived from tumor tissues, excluding sarcomas." (PMID 33792840, 2021). "The radar diagrams exhibited that CD274 level was correlated with TMB in BLCA, BRCA, CESC, COAD, KIRC, KIRP, LUAD, sarcoma (SARC), SKCM, STAD, and UCEC." (PMID 36276934, 2022). "Finally, the results of immune checkpoints’ expression showed significant differences in CD274, HAVCR2, PDCD1, and TIGIT between the two subtypes, and m7GRGs might be a predictive marker for the treatment of sarcomas by targeting immune checkpoints." (PMID 36816047, 2023). "Transcriptomics performed in the TCGA sarcoma cohort confirmed the prognostic value of combining CD11c with CD8 (259 patients, p = 0.005), irrespective of FOXP3 levels and in a CD274 (PD-LI)-rich tumor microenvironment." (PMID 33803245, 2021).
viral infection (216 papers, 2010 to 2026). "Cd274 encodes PD-L1 and its delicate balance with programmed cell death 1 (PD-1; encoded by Pdcd1) is important for restricting CD8+ T cell-induced immunopathology during both early and late virus infections." (PMID 38536871, 2024). "Furthermore, high-level co-expression of CD274 and CD8A is usually associated with higher tumor mutation and oncogenic viral infection." (PMID 33585244, 2020). "CD274 is induced by IFNs and functions in T cell costimulation during viral infection." (PMID 23029269, 2012). "Select genes that were highly expressed in COVID-19(+) TV specimens compared to COVID-19(+) PU and COVID-19(-) PU control groups play a central role in regulation of innate immune responses and defense to viral infection, including CARD8, IL1A, CD274, TRIM35, IRF7, and IFIH1." (PMID 37026002, 2023).
myeloma (205 papers, 2012 to 2026). "Primary myeloma cells as well as dendritic cells from patients express the ligand PDL1 (CD274)." (PMID 30174794, 2018). "They discovered that co-culturing pDCs with myeloma cells increases CD73, CD274, HDAC6, TLR7/9, or IL3Ra/CD123 gene expression, while reducing the expression of ADAM33, BAD, BAK1, and CASP3 in tumor cells." (PMID 39087026, 2024).